BCL2 (BCL2 apoptosis regulator)
Diseases named in the same sentence as BCL2 in open-access papers (continued):
Sharing a sentence is not in itself a finding about the gene and the disease.
acute myeloid leukemia (continued). "The use of the BCL2 inhibitor venetoclax has transformed the management of patients with acute myeloid leukemia (AML) who are ineligible for intensive chemotherapy." (PMID 37065864, 2023). "Hypomethylating agents have been successfully used in combination with the BCL-2 inhibitor, venetoclax, for the treatment of patients with acute myeloid leukemia (AML)." (PMID 36380143, 2023). "In 2017, FDA approved Venetoclax, a novel BCL-2 inhibitor targeting the PPIs between BCL-2 and other proteins in acute myeloid leukemia treatment." (PMID 36479199, 2022). "Upregulation of BAX, downregulation of Bcl-2 and increase in DNA fragmentation in acute myeloid leukemia." (PMID 35664773, 2022). "Now the selective BCL2 inhibitors have been tested in clinical trials for patients with acute myeloid leukemia, non-Hodgkin lymphoma and multiple myeloma." (PMID 35372044, 2022). "Venetoclax, a B-cell lymphoma (BCL-2) inhibitor, in combination with hypomethylating agents has become the new standard of care in elderly and unfit patients with acute myeloid leukemia, with significantly improved overall survival and quality of life." (PMID 36142863, 2022). "Several clinical reports have described how the Bcl‐2 gene is overexpressed in 84% of patients with acute myeloid leukemia (AML) at the time of diagnosis and in almost all (95%) patients who experience a relapse." (PMID 34173723, 2022). "Despite high initial response rates, acute myeloid leukemia (AML) treated with the BCL-2–selective inhibitor venetoclax (VEN) alone or in combinations commonly acquires resistance." (PMID 35185150, 2022). "More importantly, Idasanutlin has been shown to be highly effective in combination with the BCL-2 inhibitor Venetoclax against KMT2A-rearranged acute myeloid leukemia." (PMID 35327440, 2022). "Venetoclax is a selective BCL-2 inhibitor that has been approved for the treatment of chronic lymphoid leukemia and acute myeloid leukemia." (PMID 34198580, 2021). "The exposure of acute myeloid leukemia (AML) cells to BIM-2 resulted in a remarkable antitumor activity as a consequence of the drug-mediated down-regulation of both MYC and BCL2, two oncogenes the over-expression of which is associated with the development of AML." (PMID 34073075, 2021). "METTL3 upregulation increases translation of MYC, BCL2 and PTEN mRNAs in acute myeloid leukemia (AML), and METTL3 loss leads to increased levels of phosphorylated AKT, promoting differentiation of hematopoietic stem/progenitor cells (HSPCs)." (PMID 33922187, 2021). "Mouse models of high risk (HR)-MDS and acute myelogenous leukemia (AML) post-MDS using mutant NRAS and overexpression of human BCL-2, known to be poor prognostic indicators of the human diseases, were created." (PMID 34638998, 2021). "BCL-2 overexpression has been associated with resistance to chemotherapy and reduced survival in acute myeloid leukemia (AML), but few data are available in elderly patients, a subset accounting for majority of AML cases and with dismal prognosis." (PMID 34768616, 2021). "Overexpression of BCL-2 proteins in acute myeloid leukemia can circumvent resistance to apoptosis and chemotherapy." (PMID 33251145, 2020). "In other hematological malignancies, tucidinostat inhibits MYC and BCL2 in acute myeloid leukemia, and tucidinostat also downregulates BCL2 in combination with doxorubicin in peripheral T-cell lymphoma." (PMID 33097085, 2020). "A recent study demonstrated that m6A modification promotes the translation of bcl-2 mRNA in the human acute myeloid leukemia MOLM-13 cell line." (PMID 32294948, 2020). "Many acute myeloid leukaemias (AMLs) express high levels of BCL-2 and MCL-1, especially after therapy." (PMID 30470795, 2019). "Recent reports indicate that cells derived from acute myeloid leukemia (AML) patients can be effectively targeted with a BCL-2 and/or MCL-1 inhibitor, although other studies suggest that these cells depend primarily on BCL-2 for survival." (PMID 30185825, 2019).
acute myeloid leukemia (continued). "In acute myeloid leukemia, SPG6 supported development of acute myeloid leukemia by regulating BMPR2-Smad-Bcl-2/Bcl-xl signaling." (PMID 31889906, 2019). "The Bcl-2 mRNA contains the same group 3 AREs as cIAP2 mRNA and binding of HuR is reported to modulate Bcl-2 mRNA stability in HL60 acute myeloid leukemia cells and A431 epidermoid carcinoma cells." (PMID 29619127, 2018). "The study of Poeta was focused on the BAX/Bcl-2 ratio as a predictive marker for acute myeloblastic leukemia." (PMID 29515335, 2018). "When overexpressed in acute myeloid leukaemia cells, the survival proteins BCL-2 and MCL-1 confer chemoresistance." (PMID 27092880, 2017). "The objective of this study was to develop a nanoparticle system which is capable of delivering G3139 to acute myeloid leukemia (AML) cells to induce Bcl-2 downregulation and inhibit cancer cell growth." (PMID 27034925, 2016). "ABT-199, a potent and selective small-molecule antagonist of BCL-2, is beingclinically vetted as pharmacotherapy for the treatment of acute myeloid leukemia(AML)." (PMID 27283158, 2016). "The pan-Bcl-2 inhibitor (−)B197D6 induced apoptosis of acute myeloid leukemia (AML) cells by disrupting Mcl-1/Bim and Bcl-2/Bax interactions." (PMID 26405162, 2015). "Moreover, the cooperative function of Bcl‐2 and Mcl‐1 has been identified as a mechanism leading to treatment failure in acute myeloid leukemia (AML), where dual inhibition of these proteins has shown potential to improve treatment results." (PMID 40405831, 2025). "Similarly, in METTL3-deficient acute myeloid leukemia cells, c-MYC, Bcl-2, and PTEN protein levels were reduced despite a 2-5 log2-fold increase in mRNA expression." (PMID 38385075, 2024). "In this preclinical study, we assessed the IRAK4 inhibitor emavusertib (CA4948) in combination with the MCL1 inhibitor S63845, the BCL2 inhibitor venetoclax, and the HSP90 inhibitor PU-H71 in the treatment of acute myeloid leukemia and investigated the associated biomarkers of response." (PMID 38666914, 2024). "Elevated BCL-2 levels promote cancer cell survival and growth, correlating with disease progression, metastasis, and adverse clinical outcomes across several malignancies, including acute myeloid leukemia (AML) and B-cell non-Hodgkin lymphoma (B-NHL)." (PMID 39026380, 2024). "However, the only FDA approved BCL-2 family protein inhibitor for the treatment of relapsed/refractory chronic lymphoblastic leukemia (CLL) and acute myelogenous leukemia (AML) is an alternate BCL-2-selective agent, venetoclax." (PMID 38534371, 2024). "Targeting the FLT3 receptor and the IL-1R associated kinase 4 as well as the anti-apoptotic proteins MCL1 and BCL2 may be a promising novel approach in the treatment of acute myeloid leukemia (AML)." (PMID 38666914, 2024). "Venetoclax (VEN), the first selective Bcl-2 inhibitor, has shown efficacy and safety both as monotherapy and in combination with other agents in the treatment of newly diagnosed acute myeloid leukemia (AML), while its role in relapsed or refractory (R/R) disease is not well defined." (PMID 37391809, 2023). "The BCL-2 inhibitor venetoclax improves survival for adult patients with acute myeloid leukemia (AML) in combination with lower-intensity therapies, but its benefit in pediatric patients with AML remains unclear." (PMID 37046645, 2023). "Targeting the molecular chaperone HSP90 and the anti-apoptotic proteins MCL1 and BCL2 may be a promising novel approach in the treatment of acute myeloid leukemia (AML)." (PMID 37754227, 2023). "Upregulation of Bcl-2 protein denotes chemoresistance in acute myeloid leukemia." (PMID 34954697, 2022). "Furthermore, another manuscript reports that activation of the ISR overcomes the resistance to Bcl2‐inhibitors in acute myeloid leukemia." (PMID 35861150, 2022).
acute myeloid leukemia (continued). "miCLIP analysis showed that METTL3 enhanced the m6A methylation of target genes such as Bcl2, Myc and Pten in the human acute myeloid leukaemia (AML) MOLM-13 cell line, which promoted the mRNA translation of these genes, thereby retaining pluripotency properties and inhibiting cell differentiation." (PMID 36407103, 2022). "Finally, in acute myeloid leukemias (AML) resistant to the Bcl-2 antagonist venetoclax, OPA1 inhibition restores sensitivity to venetoclax." (PMID 35279198, 2022). "In THP-1 acute myeloid leukaemia cells, there was a significant decrease in the expression of BCL2, BCLX, and BAD genes and proteins; with a significant increase in TNFR1/TNFRSF1A, CASP-9, and CASP-3 gene expression, when compared to the vehicle control (P ≤ 0.05)." (PMID 35614109, 2022). "The Bcl2 inhibitor venetoclax is a breakthrough therapy in acute myeloid leukemia (AML)." (PMID 34885077, 2021). "Additionally, to test the effect of differing cellular Bcl-2 status, compounds 6a–k and 8a–b were evaluated for activity in the leukaemic cell lines KG1a (acute myelogenous leukaemia, Bcl-2 positive,) and Jurkat (T-cell leukaemia, Bcl-2 negative,)." (PMID 30986908, 2019). "For example, combining the small molecule venetoclax with the anti-CD20 rituximab may prevent some acute myeloid leukemias from bypassing BCL2 inhibition." (PMID 28685150, 2017). "The overexpression of anti-apoptotic Bcl-xL, Mcl-1 or Bcl-2 occurs frequently in cancers, particularly in hematologic malignancies such as acute myeloid leukemia (AML) and multiple myeloma (MM), resulting in defective apoptosis leading to enhanced cell survival and drug resistance." (PMID 28038464, 2017). "In human acute myeloid leukemia, gastric cancer and hepatocellular carcinoma, nobiletin significantly suppresses cell proliferation and induces apoptosis by inducing caspase signals and down-regulating the expressions of Bcl-2 and Cox-2." (PMID 27144433, 2016). "It was shown that treatment of AXL-transfected U937 acute myeloid leukaemia cells with recombinant GAS6 resulted in resistance to doxorubicin, VP16, and cisplatin, an effect associated with increased expression of the antiapoptotic molecules Bcl-2 and Twist." (PMID 23878800, 2013). "Venetoclax (VEN), a BCL-2 inhibitor, was approved in Japan in March 2021, for acute myeloid leukemia (AML)." (PMID 41857430, 2026). "Venetoclax is a clinically available Bcl2 inhibitor increasingly used to treat patients with hematological malignancies such as multiple myeloma (MM) and acute myeloid leukemia (AML)." (PMID 41610429, 2026). "In acute myeloid leukemia (AML), monocytic subtypes resist BCL2 inhibition with venetoclax, yet their metabolic dependencies remain poorly defined." (PMID 42255227, 2026). "Interestingly, elevated S100A8/A9 levels predict Venetoclax resistance in acute myeloid leukemia, suggesting that modulation of calcium-binding proteins could influence both efficacy and toxicity profiles of BCL2 inhibitors." (PMID 40715042, 2025). "Bcl-2 is also a critical player in acute myeloid leukemia (AML), promoting leukemic cell survival and contributing to resistance against conventional therapies by upregulating anti-apoptotic proteins." (PMID 40841912, 2025). "The BCL-2 inhibitor genetical has demonstrated remarkable synergy with hypomethylating agents in acute myeloid leukemia (AML), leading to its adoption as first-line therapy for older patients." (PMID 41464798, 2025). "In acute myeloid leukemia (AML), ClpP activators can destroy leukemic stem cells and help defeat resistance to BCL-2 inhibitors." (PMID 41155556, 2025). "Disruption of GSH metabolism in acute myeloid leukemia (AML) impairs ABCC1‐mediated efflux of the BCL2 apoptosis regulator (BCL‐2) inhibitor venetoclax, thereby sensitizing malignant cells to this targeted therapy." (PMID 40919131, 2025).
acute myeloid leukemia (continued). "An example is the unprecedented success of the combined use of hypomethylating agents e.g., 5-azacytidine and decitabine in combination with the Bcl-2 inhibitor venetoclax for treating acute myeloid leukemia (AML)." (PMID 39747052, 2025). "Acute Myeloid Leukemia (AML) remains a formidable clinical challenge, predominantly due to the emergence of resistance to existing therapeutic regimens, including BCL‐2 inhibitors like Venetoclax." (PMID 40305693, 2025). "Venetoclax, a selective BCL2 inhibitor, is extensively utilized in clinical settings for the treatment of acute myeloid leukemia (AML)." (PMID 40169588, 2025). "Therefore, drugs such as venetoclax, a selective inhibitor of B-cell lymphoma 2 (BCL-2), which has been used successfully in the treatment of elderly patients with acute myeloid leukemia, may be worthy of further investigation." (PMID 38883104, 2024). "BCL-2 inhibitors such as venetoclax offer therapeutic promise in acute myeloid leukemia (AML) and other cancers, but drug resistance poses a significant challenge." (PMID 39191721, 2024). "Another example of the importance of the CTS is an acquired mutation (P168A) in Bax that confers resistance of acute myeloid leukemia (AML) cells to the FDA approved Bcl-2 inhibitor, Venetoclax." (PMID 38985308, 2024). "MCL-1 and BCL-2 are typically overexpressed in acute myeloid leukemia and are required for the survival of AML cells and stem cells." (PMID 38790277, 2024). "Unfortunately, although BCL-2 inhibition has shown remarkable results in a range of B-cell lymphoid cancers as well as acute myeloid leukemia (AML), the development of resistance significantly reduces response rates in specific tumor subtypes." (PMID 39906657, 2024). "Venetoclax, an inhibitor that selectively targets B cell lymphoma-2 (BCL-2) that has been approved for treating adult acute myeloid leukemia (AML) in combination with hypomethylating agents." (PMID 38238299, 2024). "In the context of acute myeloid leukemia (AML), the induction of alkaliptosis has been shown to overcome BCL2-mediated resistance." (PMID 37601110, 2023). "Up-regulated cellular level of CLPB in acute myeloid leukemia (AML) cells was found to mediate the resistance to BCL-2 inhibitor venetoclax." (PMID 36745679, 2023). "Etomoxir was also able to increase the sensitivity of hepatocellular carcinoma (HCC) CSCs to sorafenib and showed synergy with ABT-737, a molecule targeting BCL-2, in the context of acute myeloid leukemia (AML)." (PMID 38067114, 2023). "Venetoclax is a selective B-cell lymphoma 2 (BCL-2) inhibitor now licensed in several different haematological malignancies, such as acute myeloid leukemia (AML) or chronic lymphocytic leukemia (CLL)." (PMID 35295611, 2022). "Patients with acute myeloid leukemia (AML) are routinely treated with either intensive chemotherapy or DNA hypomethylating agents (HMA) in combination with the Bcl-2 inhibitor, venetoclax." (PMID 35884414, 2022). "MCL1 (myeloid cell leukemia-1) is a closely related to BCL2 (B-cell lymphoma 2) and both frequently overexpressed in acute myeloid leukemia and critical for the survival of AML cells and AML stem cells." (PMID 35895695, 2022). "As single agents, DNMTi are currently approved for treatment of myelodysplastic syndromes (MDS) or acute myeloid leukemia (AML); in AML, also in combination with the BCL2 inhibitor venetoclax." (PMID 36497404, 2022). "Many studies reported that Bcl-2 plays a key role in acute myeloid leukemia (AML) cell survival and treatment resistance of conventional chemotherapy 12-14." (PMID 34659562, 2021). "BCL‐2 inhibition through venetoclax (VEN) targets acute myeloid leukemia (AML) blast cells and leukemic stem cells (LSCs)." (PMID 33902674, 2021). "Venetoclax, a selective BCL2 inhibitor, is approved in combination with hypomethylating agents for newly diagnosed Acute Myeloid Leukemia (AML)." (PMID 34993151, 2021).
acute myeloid leukemia (continued). "Increased BCL2 levels are also reported in acute myeloid leukemia (AML) patients, and a majority of AML blasts depend on BCL2 for survival." (PMID 34938664, 2021). "Leukemic cells from patients with chronic lymphatic leukemia (CLL) and acute myeloid leukemia (AML) showed increased expression of B-cell lymphoma-2 (Bcl-2) protein, thereby avoiding apoptosis." (PMID 33297561, 2020). "Advances in acute myeloid leukemia (AML) genomics and targeted therapies include the recently approved BCL2 inhibitor venetoclax." (PMID 33291851, 2020). "The goal of this study was to develop a nanoparticle system for delivery of ASO G3139, which targets mRNA of antiapoptotic protein Bcl-2, to acute myeloid leukemia (AML) cells." (PMID 27034925, 2016). "Indeed, BCL2 was recently shown to be a target of HOXA9 in acute myeloid leukemia." (PMID 25762636, 2015). "Thus, pLLD may induce apoptosis of the acute myeloid leukemia cells via increase of intracellular ROS, activation of the p38 pathways, and inhibition of expression of the downstream mediator Bcl-2." (PMID 25750993, 2015). "The development of targeted treatments, including inhibitors of BCL-2, FLT3, IDH1/2, and menin, has significantly expanded the therapeutic landscape of acute myeloid leukemia (AML), offering more personalized and molecularly driven treatment approaches." (PMID 41899095, 2026). "The use of the BCL2 inhibitor venetoclax in combination with hypomethylating agents (HMA) is a revolution for the treatment of frail and elderly acute myeloid leukemia (AML) patients." (PMID 41030943, 2025). "5-Azacytidine (AZA) combined with the BCL2 inhibitor Venetoclax (VEN) is the standard treatment for elderly acute myeloid leukemia (AML) patients or those who are unfit for intensive chemotherapy (elderly or unfit AML)." (PMID 39910681, 2025). "In acute myeloid leukemia (AML), the targeting of the FLT3 and BCL-2 pathways has indirectly diminished leukemic stem cells, leading to significant enhancements in survival with medicines like venetoclax." (PMID 41439922, 2025). "Similar to the synergism observed between obatoclax, a Mcl-1/Bcl-2 inhibitor, and TRAIL, another Mcl-1/Bcl-2 antagonist, venetoclax, showed synergism with the TRAIL fusion protein, eftozanermin alfa, in acute myeloid leukemia cells, as well as in patients." (PMID 41180258, 2025). "ST1326 (teglicar) is a preclinical-stage CPT1 inhibitor with demonstrated antitumor effects, particularly when combined with Bcl-2 inhibitors (e.g., ABT199) in acute myeloid leukemia (AML)." (PMID 41219902, 2025). "Clinically, the most advanced of these BH3 mimetics is venetoclax, a selective inhibitor of BCL2, which has received approval by many regulatory authorities worldwide for treating chronic lymphocytic leukemia (CLL) and acute myeloid leukemia (AML)." (PMID 40075071, 2025). "Acute myeloid leukemia (AML), the dominant acute leukemia in adults, has shown survival gains with FLT3/IDH inhibitors and Bcl-2 antagonists; however, resistance and relapse limit the 5-year survival to approximately 30%." (PMID 40690460, 2025). "Venetoclax, which inhibits BCL2, is now approved for treating chronic lymphocytic leukemia (CLL) and acute myeloid leukemia (AML)." (PMID 40204951, 2025). "In our previous studies, we demonstrated that isoflavonoid 8-hydroxydaidzein induced apoptosis by downregulating acute myeloid leukemia (AML)-associated genes such as RUNX1, CCND2, and MYC in U937 cells while upregulating CDKN1A (p21) and suppressing BCL2 expression in K562 cells." (PMID 40508126, 2025). "Most tumor stem cells in acute myeloid leukemia (AML), MDS, and CMML have high levels of BCL2 and are dependent on BCL2 for survival." (PMID 40287746, 2025).